PRDM5 (PR/SET domain 5)
Diseases named in the same sentence as PRDM5 in open-access papers (continued):
Sharing a sentence is not in itself a finding about the gene and the disease.
cancer (continued). "This was examined in both cancer and precursor lesion subgroups to give an indication of when PRDM5 is downregulated in tumourigenesis." (PMID 25613750, 2015). "In the present study, we showed that PRDM5, an epigenetic modifier gene, was frequently inactivated by promoter methylation in multiple common cancers." (PMID 22087297, 2011). "Recent reports showed PRDM5 silencing by promoter methylation in multiple cancers including breast, ovarian, colorectal, gastric, and hepatocellular tumors." (PMID 22087297, 2011). "The high incidence of PRDM5 methylation in some carcinomas indicates that it is a potential epigenetic biomarker for these tumors." (PMID 22087297, 2011). "Inhibition of NNMT leads to a methyl overflow, which enhances trimethylation of histone H3K9 and increases DNA methylation at the promoters of PRDM5 and extracellular matrix-related genes in cancer cells, therefore being regarded as a promising anti-cancer target." (PMID 40529507, 2025). "Tissue microarray showed that the protein level of PRDM5 in the adjacent tissues of patients with ESCC was higher than that in cancer tissues, and the expression level of PRDM5 was significantly correlated with the grade of clinicopathological characteristics (P < 0.001)." (PMID 35799142, 2022). "Furthermore, the cancer growth and metastasis were significantly inhibited in mice inoculated with cells undergoing PRDM5 silencing in vivo." (PMID 27485778, 2016). "CIMP high was strongly prevalent in the BRAF mutant/MSI cancers (at 86%), therefore this was evident in the BRAF mutant/MSS cohort (61% CIMP high rate) where CIMP high was more frequent in PRDM5 methylated compared to unmethylated cancers (27/36, 75.0% vs 27/53 50.9%; p = 0.03)." (PMID 25613750, 2015). "PRDM5 protein expression was assessed by immunohistochemistry in cancers and polyps." (PMID 25613750, 2015). "We then checked PRDM5 expression in multiple carcinoma cell lines." (PMID 22087297, 2011). "Similarly, knockdown of PRDM5 promoted cancer cell growth in an in vitro assay." (PMID 36127737, 2023). "More importantly, PRDM5 may also be an antioncogene or protooncogene in different types of cancer." (PMID 31119897, 2019). "The one cancer that was methylated but still expressed PRDM5 protein may be in the seeding stages of methylation, and although the relatively few CpG sites covered by the methylight assay were methylated, they were not sufficient to fully silence protein expression." (PMID 25613750, 2015). "Furthermore, PRDM5 has been associated with inhibition of the Wnt pathway, where its overexpression prevented TCF/beta-catenin dependent transcription and repressed the downstream Wnt target, CDK4 in cancer cell lines." (PMID 25613750, 2015). "Intriguingly, we found that the protein expression levels of MECOM, PRDM5, PRDM10, and PRDM11 were generally higher in UCEC tissue compared to normal tissue, while the expression of PRDM1 was diminished in cancer tissue." (PMID 39468462, 2024). "Again, selective upregulation of transcriptional and epigenetic regulators in responders is evident; examples include PRDM5, ZNF230, ZCCHC9, ZKSCAN4, and the epigenetic regulator ALKBH3, which demethylates DNA and RNA in cancer cells." (PMID 39450169, 2024). "PRDM5 (PR domain protein 5), a member of the PRDM family, acted as a new transcription repressor and a tumor suppressor in various human cancers." (PMID 35847370, 2022). "A potential role for PRDM10 in cancer is to be highly expected since several better studied members of the PRDM family, PRDM2, PRDM3, PRDM5, and PRDM14, are known to play an important role in a variety of cancers." (PMID 31143550, 2019). "PRDM5 protein expression was substantially down-regulated in both BRAF mutant and wild type cancer cohorts (92/97,95% and 39/44,89%)." (PMID 25613750, 2015). "When the BRAF mutant cancers were stratified for MSI status, it was apparent that PRDM5 methylation correlated with CIMP." (PMID 25613750, 2015).
cancer (continued). "Despite the finding that the suppression of WNT/β‐catenin signaling on account of ectopic PRDM5 expression was determined in limited cancer cell lines, we first explored and identified the inhibition of JAK2/STAT3 pathway in LUAD cell lines with PRDM5 overexpression." (PMID 36127737, 2023). "In addition, PRDM5 protein levels were significantly reduced in both mutant and wild-type intestinal polyps, especially in BRAF mutant and wild-type cancers." (PMID 35799142, 2022). "Epigenetic modification may be contributing to gene silencing in a proportion of BRAF mutant cancers and the large extent of absent protein expression indicates other mechanisms are also responsible for PRDM5 down-regulation." (PMID 25613750, 2015). "Interestingly the vast majority of cancers in both the BRAF mutant and BRAF wild type cancer cohorts lacked PRDM5 protein expression." (PMID 25613750, 2015). "This analysis also revealed a number of epigenetic oncogenes (KDM1A, HDAC1, TDG) and tumor suppressors (KAT2B, PRDM5, DUSP1, EYA4) which did not correlate significantly with any of the others, suggesting that these may affect cancer DNAm patterns independently of each other." (PMID 26169266, 2015).
connective tissue disorder (6 papers, 2013 to 2025). A disease involving the connective tissue. "Furthermore, BCS2 is an inherited connective tissue disorder with PRDM5 being one of the most often mutated genes." (PMID 38589350, 2024). "A definitive diagnosis and differentiation from other connective tissue disorders can be established through genetic testing, which identifies mutations in the ZNF469 gene (Type 1) and PRDM5 gene (Type 2)." (PMID 40647596, 2025). "PRDM5 is involved in the development and maintenance of the extracellular matrix (ECM), which explains its involvement in BCS and ARS syndromes, which represent multisystemic connective tissue disorders." (PMID 26489929, 2016).
PRDM5 also shares sentences with these, for which no sentence is quoted: acute myelogenous leukemia (2 papers); adenocarcinoma (1); Aortic Aneurysmal Disease (1); bladder cancer (1); brain glioma (1); breast tumors (1); cervical incompetence (1); diffuse large B-cell lymphoma (1); esophagitis (1); hearing loss (1); hyperlipidemia (1); Hypertension (1); lung squamous cell carcinoma (1); metabolic disease (1); nasopharyngeal carcinoma (1); ovarian carcinoma (1); prostate adenocarcinoma (1); prostate carcinoma (1); uterine corpus endometrial carcinoma (1); viral infections (1); Werner syndrome (1).